GPHN (gephyrin)
Description:
Microtubule-associated protein involved in membrane protein-cytoskeleton interactions. It is thought to anchor the inhibitory glycine receptor (GLYR) to subsynaptic microtubules (By similarity). Acts as a major instructive molecule at inhibitory synapses, where it also clusters GABA type A receptors. Also has a catalytic activity and catalyzes two steps in the biosynthesis of the molybdenum cofactor. In the first step, molybdopterin is adenylated. Subsequently, molybdate is inserted into adenylated molybdopterin and AMP is released.
Synonyms: GPH; KIAA1385; GEPH; GPHRYN; HKPX1; MOCODC
Tractability: Small molecule: it has a high-quality binding pocket. Antibody: UniProt places it where antibodies can reach, with high confidence; its Gene Ontology location is reachable by antibodies, with high confidence. PROTAC: ubiquitination databases record sites on it; its protein half-life has been measured.
Gene: Protein-coding gene on chromosome 14 (66,507,407 to 67,181,803, forward strand). Ensembl gene ENSG00000171723.
Subcellular location: Postsynaptic cell membrane; Cell membrane; Cytoplasm, cytosol; Cytoplasm, cytoskeleton; Cell projection, dendrite; Postsynaptic density
Subcellular location (Human Protein Atlas): Vesicles; Cytosol
Pathways (Reactome):
Metabolism: Molybdenum cofactor biosynthesis
Gene Ontology:
Molecular function: identical protein binding; molybdopterin cofactor binding; nitrate reductase activity; protein binding; protein-macromolecule adaptor activity; molybdopterin molybdotransferase activity; catalytic activity; molecular adaptor activity; molybdopterin adenylyltransferase activity; signaling receptor binding
Biological process: gamma-aminobutyric acid receptor clustering; Mo-molybdopterin cofactor biosynthetic process; response to metal ion; establishment of synaptic specificity at neuromuscular junction; glycine receptor clustering; establishment of protein localization; molybdopterin cofactor biosynthetic process; neurotransmitter receptor localization to postsynaptic specialization membrane; protein localization to membrane; synapse assembly; synapse organization
Cellular component: cytosol; dendrite; dendritic spine; postsynaptic membrane; synaptic membrane; cytoplasm; plasma membrane; postsynaptic density; postsynaptic specialization; cytoplasmic side of plasma membrane; cytoskeleton; GABA-ergic synapse; glycinergic synapse; inhibitory synapse; postsynapse; postsynaptic specialization, intracellular component
Genetic constraint (gnomAD): Loss-of-function variants: 3 observed, 32.31 expected, observed/expected ratio (o/e) 0.0928, 90% interval 0.041 to 0.24. The upper end of that interval is the gene's LOEUF score, 0.24, which puts it in group 1 of 6, group 1 being the genes least tolerant of losing a copy. Missense variants: 301 observed, 473.63 expected, observed/expected ratio (o/e) 0.64, 90% interval 0.58 to 0.7. Synonymous variants: 162 observed, 164.35 expected, observed/expected ratio (o/e) 0.99, 90% interval 0.87 to 1.12.
Gene-disease validity (ClinGen):
ClinGen rates the evidence that GPHN causes each of these diseases.
sulfite oxidase deficiency due to molybdenum cofactor deficiency type C (autosomal recessive): Moderate.
Homologues: Orthologues: macaque GPHN (99% identical), pig GPHN (99% identical), mouse Gphn (99% identical), rat Gphn (99% identical), tropical clawed frog gphn (97% identical), chimpanzee GPHN (96% identical), zebrafish gphna (94% identical), zebrafish gphnb (92% identical), rabbit GPHN (91% identical), guinea pig GPHN (87% identical), Drosophila melanogaster cin (32% identical), Caenorhabditis elegans moc-2 (10% identical).
Diseases named in the same sentence as GPHN in open-access papers:
GPHN is named in the same sentence as 66 diseases in open-access papers, as found by Europe PMC text mining. Sharing a sentence is not in itself a finding about the gene and the disease. The quoted sentences say what the papers report.
epilepsy (19 papers, 2012 to 2025). A brain disorder characterized by episodes of abnormally increased neuronal discharge resulting in transient episodes of sensory or motor neurological dysfunction, or psychic dysfunction. "Expression of aberrant GPHN splice variants is associated with several neurological disorders such as epilepsy, autism, schizophrenia, Alzheimer’s disease, and hyperekplexia, prompting a deeper understanding of the regulation of GPHN splice variants in humans." (PMID 35717442, 2022). "Gephyrin dysfunctions are further found in other neurological diseases, including stiff-man syndrome, schizophrenia, autism, epilepsy, hyperekplexia, and molybdenum cofactor deficiency." (PMID 32977518, 2020). "Our study strengthens previous associations of GPHN with epilepsy and expands the phenotypic spectrum with EEs." (PMID 26613940, 2015). "Mutations in several GABAAR subunit‐encoding genes, including the synaptic subunits GABRA1, GABRB3, and GABRG2 that associate with gephyrin, have been identified in epilepsy syndromes of different degrees of severity." (PMID 26613940, 2015). "Previous studies have shown that heterozygous exon‐disrupting deletions in GPHN are a risk factor for epilepsy." (PMID 26613940, 2015). "Our findings strengthen previous associations of GPHN with epilepsy and other neurodevelopmental disorders and expand the spectrum to an infantile onset EE." (PMID 26613940, 2015). "These early signal transduction changes may also underlie the rapid effects of GPHN in the epilepsy model." (PMID 40346986, 2025). "Deficient GPHN function, as indicated by decreased expression in our samples, impairs inhibitory GABAergic synaptic activity, which results in hyper-excitability of neural cells, as seen in epilepsy." (PMID 36386965, 2022). "In addition, dysfunction of GPHN-mediated neurotransmission has been implicated in severe disorders, such as Alzheimer’s disease, autism, schizophrenia, epilepsy, and also in hyperekplexia." (PMID 35717442, 2022). "Abnormal GPHN clustering during neurodevelopment is associated with the pathogenesis of neurological, neurodevelopmental, and psychiatric disorders, with exonic deletions implicated in the risk for schizophrenia, autism, and epilepsy development." (PMID 36386965, 2022). "Interestingly, gephyrin malfunction has also been linked to neuropsychiatric diseases including epilepsy." (PMID 25025157, 2014). "While gephyrin exonic microdeletions and missense mutations are associated with autism, schizophrenia, and epilepsy in humans, whether gephyrin phosphorylation is relevant for the establishment of inhibition during postnatal sensitive periods has not been examined." (PMID 38503929, 2024). "Impairments in CB‐dependent synaptic gephyrin clustering lead to severe neurological dysfunctions such as epilepsy, anxiety, aggression, and intellectual disabilities." (PMID 40781785, 2025). "Gephyrin is closely related to epilepsy, autism, schizophrenia, and other neuropsychiatric disorders." (PMID 36438847, 2022). "The specific mechanisms involved in the regulation of gephyrin during epileptogenesis and epilepsy remain to be fully characterized, but some clues are starting to emerge." (PMID 23885234, 2013). "Based on previous microarray results, we identified a lncRNA specifically downregulated in epilepsy: IncRNA‐NONRATTO25141.2, which is located in the first intron of the Gephyrin (GPHN) gene on rat chromosome 6." (PMID 40346986, 2025). "Collybistin mutants with reduced lipid binding affinity disrupt GABAergic synapses by preventing gephyrin synaptic clustering and GABAA receptor targeting and this was in turn reported to trigger epilepsy." (PMID 37228704, 2023). "We first investigated levels of the presynaptic marker synaptophysin, the excitatory postsynaptic marker PSD95 and the inhibitory postsynaptic marker gephyrin in hippocampus and temporal lobe samples at SE, LP and SRS stages of epilepsy." (PMID 31356824, 2019).
epilepsy (continued). "If a loss of gephyrin directly impacts the number and function of GABAAR at inhibitory synapses, interventions to promote the stability of gephyrin and GABAAR might ameliorate the deleterious changes in excitability observed during epileptogenesis and epilepsy." (PMID 23885234, 2013). "Pin1 has strong neuroprotective effects in the progression of epilepsy, and the Pin1/NMDAR complex, Pin1-CaMKII-AMPA receptor axis and Pin1-NL2/gephyrin- GABAergic signaling may all be involved in the mechanism." (PMID 36304997, 2022). "Given the importance of gephyrin in the organization of inhibitory synapses, it is not surprising that gephyrin dysfunction can lead to epilepsy." (PMID 26613940, 2015). "The references selected in this study were mainly clustered in 14 categories: anxiety, tolerance, mitochondria, epilepsy, pharmacokinetics, midazolam, hypnotics, intranasal formulation, outcomes, cancer, gamma-aminobutyric acid (GABA), astrocytes, febrile seizures, GABAR, and gephyrin." (PMID 36438847, 2022). "Research shows that, during epilepsy (incubation period), the levels of total gephyrin and GABAAR subunits γ2, α2/3, and α4 protein in the hippocampus of animals decreased significantly, and gephyrin knockout mice died in a state similar to status epilepticus within 24 h of birth." (PMID 36438847, 2022). "Therefore, elucidating the detailed molecular mechanism of the gephyrin-independent regulation of GABAAR lateral mobility might contribute not only to understanding the basis of learning and memory but also to discovering therapeutic targets for neuropathies such as epilepsy." (PMID 22563445, 2012).
autism (15 papers, 2010 to 2024). Persistent deficits in social interaction and communication and interaction as well as a markedly restricted repertoire of activity and interest as well as repetitive patterns of behavior. "We here add the autism risk factor Met as a further receptor tyrosine kinase to regulate gephyrin clustering." (PMID 34054427, 2021). "We further show that an autism-associated mutation inhibits the gephyrin-dependent pathway while a phosphorylation site is responsible for modulating the gephyrin-independent pathway." (PMID 27805570, 2016). "In light of the fact that rare exonic deletions implicate gephyrin in risk for autism, schizophrenia and seizures, these findings make rTMS an interesting clinical tool for the modulation of gephyrin-mediated inhibitory synaptic plasticity." (PMID 27965542, 2016). "These domains point to a gephyrin-dependent mechanism that is disrupted by an autism-associated mutation at R705 and a gephyrin-independent mechanism reliant on a putative phosphorylation site at S714." (PMID 27805570, 2016). "Given the central role of mTOR for the stabilization of inhibitory synapses dependent on Met signaling, it is conceivable that Tsc2, another autism risk gene and negative regulator of mTOR, might also be involved in gephyrin clustering." (PMID 34054427, 2021). "Interestingly, recent studies have similarly implicated mutations in the gephyrin gene as risk for autism and schizophrenia." (PMID 28682238, 2017). "Moreover, de novo CNV analyses indicate an enrichment of genes of the PSD95 complex in schizophrenia, and rare exonic deletions implicate Gephyrin as a risk factor for autism, schizophrenia and seizures." (PMID 24633176, 2014). "Moreover, our results, together with results from previous studies, link CB and gephyrin to biological pathways associated with autism, which make these proteins also plausible candidates for autism susceptibility." (PMID 20858277, 2010). "Besides, gephyrin dysfunctions are also linked to other neurological diseases, like stiff-person syndrome, hyperekplexia, molybdenum cofactor deficiency, schizophrenia, and autism." (PMID 31137749, 2019). "For a link of the autism risk gene MET to the reorganization of GABAergic synapses, we first examined the colocalization of Met protein with the inhibitory synaptic marker gephyrin in primary hippocampal cultures and rat brain tissue." (PMID 34054427, 2021).
Anxiety (14 papers, 2018 to 2025). Intense feelings of nervousness, tension, or panic often arise in response to interpersonal stresses. "In conclusion, interrupting gephyrin‐GABAARs interaction caused increased anxiety levels in rats." (PMID 38965798, 2024). "Similar lentivirus encoding a gephyrin mutant in which Cys284 was replaced by alanine (LV‐GphnC284A) was constructed to determine the role of S‐nitrosylation at Cys284 in the functional domain of gephyrin in modulating anxiety‐like behaviors." (PMID 38965798, 2024). "DHM restores GABAergic neurotransmission in mice, increases intracellular ATP levels, and enhances gephyrin expression, thereby improving anxiety-like behaviors." (PMID 40740995, 2025). "Further experiments are still required in the future, such as evaluating the relative magnitude of changes in gephyrin nitrosylation and palmitoylation in high anxiety rats." (PMID 38965798, 2024). "Together, the findings indicated that SNO‐gephyrin aggravates anxiety‐like behaviors by reducing the surface expression of GABAAR γ2." (PMID 38965798, 2024). "The normalization of the cytoplasmic gephyrin aggregates correlates well with the partial normalization of sIPSC frequency and amplitude, as well as with the partial normalization of the anxiety behavior in the female Nlgn2/MDGA1 dKO mice." (PMID 39284869, 2024). "Our study identified an essential role of S‐nitrosylation of gephyrin in anxiety‐like behaviors and demonstrated that the regulation of this S‐nitrosylation mediated the mechanism underlying the anxiolytic effect induced by physical exercise." (PMID 38965798, 2024). "Either pharmacological inhibition or genetic knockdown of nNOS decreased SNO‐gephyrin and alleviated the anxiety‐like behaviors of rats." (PMID 38965798, 2024). "Socially isolated mice showed increased anxiety levels, reduced exploratory behaviors, and reduced gephyrin levels." (PMID 34983568, 2022). "DHM reduces neuroinflammation, restores GABAergic function by upregulating gephyrin levels, and decreases serum cortisol levels, therefore, improves the social isolation induced anxiety and the early onset of AD." (PMID 34983568, 2022). "Collectively, our data suggest that reduction in intracellular ATP and gephyrin contribute to the development of anxiety, and represent novel treatment targets." (PMID 32742262, 2020). "Evidence of neuroplastic changes on gephyrin would suggest that DHM provided not only acute symptom relief but also long-lasting plastic changes of anxiety circuits, a substantial paradigm shift for the treatment of anxiety." (PMID 32742262, 2020). "DHM treatment restored ATP and gephyrin expression, GABAergic transmission and synaptic function, as well as decreased anxiety-like behavior." (PMID 32742262, 2020). "Interestingly, all three astroglial markers were negatively correlated with anhedonia-like behaviors, while SYN1 and GPHN negatively correlated with anxiety-like behaviors." (PMID 41516045, 2025). "Thus, more evidence needs to be provided in future studies to explain the regulation of anxiety by SNO‐gephyrin." (PMID 38965798, 2024). "We show that combined deletion of Nlgn2 and MDGA1 results in a partial reversal of the prominent anxiety phenotype observed in female Nlgn2 KO mice, consistent with the normalization of gephyrin aggregates and the partial normalization of sIPSC frequency in CA1 pyramidal neurons." (PMID 39284869, 2024). "We show that loss of MDGA1 expression, but not heterozygous deletion of MDGA2, ameliorates the abnormal cytosolic gephyrin aggregation, the reduction in inhibitory synaptic transmission and the exacerbated anxiety-related behaviour characterizing Nlgn2 knockout (KO) mice." (PMID 39284869, 2024). "Given this correlation, it is conceivable that the formation of these gephyrin aggregates contributes to the anxiety phenotype in the Nlgn2 KO mice, and that reversing gephyrin aggregate formation may ameliorate this behavior." (PMID 39284869, 2024).
Anxiety (continued). "In addition, selective inhibition of nNOS activity or site‐directed mutagenesis of S‐nitrosylated cysteine residues in gephyrin reduced anxiety‐like behaviors." (PMID 38965798, 2024). "In addition, blockade of gephyrin‐GABAAR signaling using GABAAR α3 subunit‐derived peptides aggravated anxiety‐like behaviors, which was in consistence with our previous findings." (PMID 38965798, 2024). "Next, we asked whether S‐nitrosylation of gephyrin at specific cysteine residues was involved in anxiety‐like behaviors." (PMID 38965798, 2024). "It was shown that the amplitude of mIPSCs was increased in the LV‐GphnC212A group compared with that of LV‐eGFP group, with no change in the frequency, indicating that sGABAAR γ2 expression modulated by inhibition of SNO‐gephyrin at Cys212 is essential for improving anxiety‐like behaviors." (PMID 38965798, 2024). "Next, we wondered whether nNOS‐mediated increase in the expression of SNO‐gephyrin would increase anxiety‐like behaviors in rats." (PMID 38965798, 2024). "The reduction of gephyrin nitrosylation may also promote the aggregation of GABAAR at synaptic sites by increasing the palmitoylation of gephyrin, thereby improving anxiety‐like behaviors." (PMID 38965798, 2024). "In summary, we identified an essential role of SNO‐gephyrin‐mediated inhibitory neurotransmission in anxiety‐like behaviors, which could be alleviated by wheel‐running exercise." (PMID 38965798, 2024). "The finding that SNO‐gephyrin is downregulated by exercise to alleviate anxiety not only provides a potential target for the prevention and intervention of anxiety, but also provides clues for the development of more effective exercise prescriptions for the treatment of anxiety and mood disorders." (PMID 38965798, 2024). "Taken together, these results suggest that SNO‐gephyrin is elevated in high‐anxiety rats." (PMID 38965798, 2024). "In this study, we found that social isolation induced anxiety-like behaviors in mice, increased corticosterone level, down-regulated gephyrin expression, enhanced the activation of NF-kB p65 pathway, decrease hippocampal microglial cell number, and increase the reactive microglia." (PMID 34983568, 2022). "Taking into consideration that GABAAR expression is ubiquitous in the brain and the primary role of GABA neurotransmitter in anxiety pathogenesis, a reduction in gephyrin protein level might provide a partial explanation of the behavioral changes shown in." (PMID 34983568, 2022). "To test the hypothesis that DHM administration ameliorates anxiety and better understand the cellular mechanisms on gephyrin, we induced anxiety in mice via social isolation and measured anxiety-like behavior." (PMID 32742262, 2020). "Taken together, these observations indicate that enhanced gephyrin nitrosylation is an important cause of anxiety, and pharmacological inhibition on gephyrin nitrosylation can increase the surface expression of GABAAR and alleviate anxiety‐like behaviors in rats." (PMID 38965798, 2024). "We also demonstrated that physical exercise rescued the impairment in GABAergic transmission at least in part by reducing the expression of SNO‐gephyrin, ultimately improving anxiety‐like behaviors, revealing a previously unknown pathway by which exercise relieved anxiety‐like behaviors." (PMID 38965798, 2024). "In mice with AD accompanied by anxiety, GABAA receptor function is impaired, and gephyrin expression is reduced; however, DHM reverses these effects." (PMID 40740995, 2025). "It is found that the level of SNO‐gephyrin is significantly increased in the BLA of high‐anxiety rats and a downregulation of SNO‐gephyrin at cysteines 212 and 284 produced anxiolytic effect." (PMID 38965798, 2024). "Recent studies have shown that diazepam can activate DHHC12 to increase the palmitoylation of gephyrin in the basolateral amygdala, rapidly reduce lateral diffusion of GABAAR, increase synaptic stability and aggregation, and play an anti-anxiety role." (PMID 36438847, 2022).